CPT1A (carnitine palmitoyltransferase 1A)
Diseases named in the same sentence as CPT1A in open-access papers (continued):
Sharing a sentence is not in itself a finding about the gene and the disease.
Hepatic steatosis (continued). "In conclusion, the present study demonstrated that proanthocyanidins from I. lactea ameliorated lipid metabolism and attenuated hepatic steatosis in mice with HFD/STZ-induced T2DM, for which activation of AMPK/ACC/CPT1A signaling might be an underlying mechanism." (PMID 32188147, 2020). "Interestingly, FGF21 overexpression partially restored the expression of PPARα and its target genes, Acox1, Hmgcs2 and Cpt1a in Creb3l3−/− mice, which might have helped to improve the hepatic steatosis." (PMID 27301791, 2016). "12-Tridecenoic acid aggravated hepatic steatosis by promoting acetyl-coenzyme A carboxylase alpha (ACC) expression and inhibiting carnitine palmitoyltransferase 1A (CPT1A) expression." (PMID 39246653, 2024). "At the same time, in HFD-induced NAFLD rats, BBR-induced activation of SIRT3, a crucial gene for fatty acid oxidation, alters the expression of ACC and carnitine palmitoyltransferase-1A (CPT-1A), thereby reducing hepatic steatosis." (PMID 38034996, 2023). "We determined that BAP31 deficiency decreased CPT1a, Acaa1a and Acads expression, which are responsible for peroxisomal and mitochondrial fatty acid β-oxidation, in KO mice under ER stress, suggesting that BAP31 deficiency may impair fatty acid oxidation in mice, and lead to liver steatosis." (PMID 30081561, 2018). "At the molecular level, HFD-NRF mice exhibited significant upregulation of hepatic fatty acid oxidation genes (particularly CPT1A), reflecting the characteristic gene expression patterns observed in clinical studies of TRF-induced improvement in hepatic steatosis." (PMID 40562101, 2025). "Our results showed the expression of ACSL5,4,3 genes significantly decreased with the severity of hepatic steatosis, and the rate-limiting enzyme CPT1A was almost not expressed in steatotic livers (Padj < 0.05, β = 45.17, post hoc Wilcoxon rank-sum test, 67 times higher in eCtrl than eHS-II)." (PMID 38837944, 2024). "Significantly decreased CPT1A in ADH− versus ADH+ deer mice fed 3.5% EtOH and decreased ratios for p-AMPK/AMPK and p-ACC1/ACC1 could be key determinants for increased EtOH-induced hepatic steatosis in ADH− deer mice fed 3.5% EtOH." (PMID 31581705, 2019).
Obesity (66 papers, 2010 to 2026). Accumulation of substantial excess body fat. "In our PCOS model, androgen-induced obesity was associated with the downregulation of lipogenesis markers, increased adipogenesis (higher C/EBPβ activity), and upregulation of CPT1A and CPT1B key thermogenesis and mitochondrial biogenesis markers." (PMID 38987854, 2024). "Particularly, CPT1A response to ATRA is impaired in those individuals with higher metabolic risk (overweight-obesity and low HDL levels), providing additional evidences of its previously reported role as a metabolic risk predictive biomarker." (PMID 32751185, 2020). "We found DMP cg00574958 annotated to gene CPT1A to be significantly associated with BMI, WC, obesity and abdominal obesity." (PMID 28947923, 2017). "A recent report done in Alaska Native Health Research showed the relationship between genetic variants of CPT1A and obesity traits." (PMID 27127449, 2016). "Decreased methylation status at the CPT1A locus has been associated with lipid profile, insulin resistance, and metabolic syndrome, as well as obesity in GOLDN, and some of these findings were replicated in other populations." (PMID 27777315, 2016). "Besides, CPT1A methylation is associated with circulating adiponectin levels, likely in an obesity-dependent manner, which can be a novel pleiotropic marker of chronic disease risk." (PMID 37033619, 2023). "Furthermore, several single nucleotide polymorphisms were identified in CPT1A of Yup’ik Eskimos, which exhibit fasting-lipid and obesity phenotypes." (PMID 28814270, 2017). "Two population based studies have shown association of sequence variants in CPT1A with various indices of obesity including waist circumference, but the exact mechanism by which CPT1A might contribute to altered adiposity remains unknown." (PMID 26798409, 2016). "Also, cg00574957 in CPT1A was negatively associated with FI and IR in both our and previous studies, showing the biological plausibility of its association with IR, including its role in obesity, metabolic syndrome, and fatty acid metabolism." (PMID 36782224, 2023). "For the cpt1a gene, a slight increase in expression was observed as obesity developed, in both in the “DIO” and “DIO+OEA-DS” groups." (PMID 40265441, 2025). "According to Soler-Vázquez and their colleagues, in obese mice transplanted with adipose-derived mesenchymal stem cells (AD-MSCs) expressing CPT1A, hyperglycemia decreased, and obesity improved." (PMID 41439952, 2025). "In a mouse model of obesity induced by a high-fat diet, the level of H3K9me was significantly increased in the promoter region of CPT1A, which subsequently downregulated CPT1A expression and thus hindered fatty acid oxidation." (PMID 40606607, 2025). "Nevertheless, all these obesity-associated pathways were annotated from only 3 genes, namely ABCG1, CPT1A, and SREBF1." (PMID 40702573, 2025). "By regulating this key step, CPT1A prevents lipid accumulation, maintains lipid homeostasis, and contributes to the prevention and treatment of obesity and metabolic syndrome-related disorders." (PMID 41439952, 2025). "The obesity and diabetes genes fat mass and obesity-associated (FTO), carnitine palmitoyl transferase 1A (CPT1A), leptin receptor (LEPR), and lamin A/C (LAMIN) genes were significantly down-regulated in the cardamom group." (PMID 38558676, 2024). "For decades, drugs targeting CPT1A have been the focus of research on diseases like type 2 diabetes (T2D), obesity, and other disorders." (PMID 37033619, 2023). "Overexpressing CPT1A, the rate limiting step in fatty acid oxidation, specifically in the hypothalamus also induced obesity mimicking the effect of CBP knockdown." (PMID 33917812, 2021). "Only six out of the 81 mitochondrial protein-encoding genes showed higher expression in the obesity-risk genotype (SEPT4, PYCR1, PRELID2, CPT1A, MTHFD1L, and FKBP10)." (PMID 32316277, 2020).
Obesity (continued). "The CPT1A gene can induce mouse obesity through diet, and its expression positively correlated with BMI (R = 0.46)." (PMID 31341893, 2019). "In our study population, CPT1A attributed to 6.1% of the variance in obesity and 5.6% of the variance in abdominal obesity." (PMID 28947923, 2017). "The odds for the obesity were 0.85, 1.04 and 0.94 for the DMPs annotated to genes CPT1A, NLRC5 and BCAT1, respectively." (PMID 28947923, 2017). "DMP cg00574958 annotated to gene CPT1A was the only DMP associated with all outcomes analysed, attributing to 6.1 and 5.6% of variance in obesity and abdominal obesity, respectively." (PMID 28947923, 2017). "The DMPs annotated to genes CPT1A, NLRC5 and BCAT1, which were associated with three out of four anthropometric indices studied, combined attributed to 7.6% of the variance on obesity." (PMID 28947923, 2017). "CPT1A, or carnitine palmitoyltransferase 1A, has been reported in relation to BMI, obesity and weight gain in both GWAS and EWAS of multiple populations." (PMID 28947923, 2017). "Fasting (which produces pro-obesity phenotypes such as hyperphagia and reduced metabolic rate) also induces Cpt1a using the same dissection." (PMID 27832201, 2016). "This included protein kinase C elipson (PRKCE), known to be involved in brain tumors, carnitine palmitoyltransferase I (CPT1A), 11β-hydroxysteroid dehydrogenase type 1 (HSD11B1) and apolipoprotein B (APOB) which are all linked to obesity." (PMID 20502671, 2010). "Similarly, its activation alleviated obesity but also occurred in the early stages of obesity, accompanied by the upregulated carnitine palmitoyltransferase 1 A (Cpt1a), and the aberrant expression of TCA cycle and electron transport chain (ETC) related genes." (PMID 41501784, 2026). "Although we showed that increased MAPK activation partially explains Coriobacteriaceae enrichment in obesity-related CRC, the mechanism underlying CPT1A upregulation in CRC remains unknown and require further study." (PMID 38245554, 2024). "Patients with metabolic syndrome, obesity, and type 2 diabetes frequently have non-alcoholic fatty liver disease, hypertriglyceridemia, and other lipid metabolism abnormalities, which can be somewhat improved by increasing CPT1A expression." (PMID 37033619, 2023). "Our results suggest that CPT1A in AgRP neurons affect food intake and the peripheral energy balance in a sex-dependent manner, highlighting this enzyme as a possible target for therapeutic strategies that aim to decrease body weight and fight obesity." (PMID 36966335, 2023). "We suggest that CPT1A should be considered as a new target against obesity." (PMID 36966335, 2023). "In this example, 16 DMSs in genes, such as CPT1A, ABCG1, SLC7A11, RNF145, and SREBF1 were reported to be associated with obesity-related phenotypes." (PMID 35047011, 2021). "This led to rapid obesity and increased expression of CPT1a." (PMID 29892261, 2018). "6.1% of variation in obesity was attributable to CPT1A alone and 5.6% for abdominal obesity." (PMID 28947923, 2017). "The DMP annotated to gene CPT1A, which was significantly hypo-methylated in individuals with obesity, was also significantly hypo-methylated in individuals with abdominal obesity compared with those without, with similar odds (OR = 0.84, 95% CI 0.79–0.90) for abdominal obesity as for obesity." (PMID 28947923, 2017). "Several points of evidence suggest that CPT-1 may be a promising target for the development of therapeutic agents against diabetes and obesity; however, a better understanding of metabolic changes following CPT1A manipulation is needed." (PMID 26808626, 2016). "As the methylation of CPT1A contributes to increased risk of obesity in several populations, it is not surprising that CPT1A methylation is highly correlated with PPL responses, likely linked to risk of CVD." (PMID 27777315, 2016).
Obesity (continued). "In conclusion, the probiotic L. reuteri strain ATCC PTA 4659 partly prevented diet-induced obesity, possibly via a previously unknown mechanism of inducing liver expression of Cpt1a." (PMID 23056479, 2012). "Given the adaptive response in fatty acid oxidation in rodent models exposed to excess lipid, the question remains whether overexpression of CPT1A in vivo can provide a route for metabolism of excess lipid and prevent impairments in endocrine function in models of obesity and T2D." (PMID 39814231, 2025). "Similarly, in the present study, the ATCC strain induced expression of Cpt1a in the liver, might provide an alternate mechanism to combat insulin resistance and obesity in a hypercholesterolemic setting." (PMID 23056479, 2012). "Specifically, the upregulation of carnitine palmitoyltransferase 1A (Cpt1a), a pivotal enzyme involved in FAO, has been identified as a key factor in obesity-induced T cell dysfunction and the subsequent enhancement of tumor growth." (PMID 41200178, 2025). "Studies have shown that FXR agonists confer renal protection in obesity-related CKD by downregulating SREBP-1 and upregulating PPARα, CPT1a, and PGC-1α." (PMID 39765868, 2024). "Among the measurement of the obesity and diabetes genes, the expression level of FTO, CPT1A, LEPR, and LAMIN were significantly downregulated in the intervention group after intervention with green cardamom (P < 0.001)." (PMID 36522620, 2022). "CPT1A, one of the key enzymes in FAO, can revert HFD-induced obesity and NAFLD in mice by enhancing liver FAO." (PMID 36432651, 2022). "This study demonstrated that a green cardamom intervention improved anthropometric indices, glycemic indices, and sexual hormones, as well as the expression level of obesity and diabetes genes FTO, CPT1A, LEPR, LAMIN, and PPAR-γ genes in PCOS women." (PMID 36522620, 2022). "PBMC mRNA levels of CPT1A, FASN and SREBP-1c increased in the OW-OB group, according with what described in liver and adipose tissue of humans with obesity." (PMID 34526523, 2021). "Higher mRNA levels of CPT1A, FASN and SREBP-1c genes in PBMC in the OW-OB group confirmed a clear impact of overweight and obesity on lipid metabolism, as we previously reported in rodents." (PMID 34526523, 2021). "In essence, our findings imply that the identified epigenetic loci at CPT1A, SREBF1, and ABCG1 can link obesity to hyperlipidemia (high TG) and elevated postprandial TG response, and then to the risk of CVD." (PMID 27777315, 2016). "In rodent studies, limiting dietary cysteine availability increased CPT1a mRNA and protein expression in inguinal adipose tissue (in line with the anti-obesity effects of the diet), but not in liver." (PMID 36542145, 2023). "By enhancing the expression of fatty acid oxidation related factors in epididymal fat (PGC-1α, PPARα, and CPT-1a), activation of BAT and WAT browning, suggesting that MA treatment can improve obesity by regulating lipid metabolism and promoting energy expenditure." (PMID 33767670, 2021). "Notably, we found three DMPs or loci (CPT1A, NLRC5 and BCAT1) that showed epigenome-wide significance with both obesity and abdominal obesity." (PMID 28947923, 2017). "Our most striking observation is the highly significant association between the CPT1A-related CpG sites and HTGW, which was independent of related phenotypes (blood pressure, obesity and T2D)." (PMID 26798409, 2016). "Additionally, compound 1 (procyanidin B2) activated fatty acid oxidation regulators, PPARα and CPT1A, and suppressed fatty acid synthesis by downregulating fatty acid synthase (FAS) expression, emphasizing its potential role in modulating obesity-related markers in 3T3-L1 preadipocytes." (PMID 38613069, 2024). "Gene expression levels of CPT1A and SREBP-1c remained higher than in NW subjects during the whole intervention period, suggesting that they reflect deeper alterations in humans with overweight and obesity, which are not easily recovered by body fat loss." (PMID 34526523, 2021).
Obesity (continued). "Hence, it is not possible to determine any potential contribution of obesity to increased CPT1A expression or overall survival in this cohort." (PMID 28101337, 2017). "In contrast, only three DMPs—cg00574958, cg07839457 and cg20399616—, annotated to genes CPT1A, NLRC5 and BCAT1, respectively, were significantly differentially methylated in those with obesity compared with those without." (PMID 28947923, 2017).
ovarian carcinoma (36 papers, 2013 to 2025). A malignant neoplasm originating from the surface ovarian epithelium. "CPT1A was found to be highly expressed in ovarian cancer, and its overexpression is linked to a poor survival in ovarian cancer patients." (PMID 37033619, 2023). "CPT1A inactivation reduced cellular ATP levels and caused cell cycle arrest at G0/G1 stage, implying that ovarian cancer cells rely on CPT1A-mediated FAO for cell cycle progression." (PMID 37033619, 2023). "Studies have demonstrated that CPT1A is highly expressed in ovarian cancer, and its overexpression is associated with poor prognosis." (PMID 33381539, 2020). "Analysis of database revealed that overexpression of CPT1A was associated with poor survival in ovarian cancer patients." (PMID 33194756, 2020). "CPT1A deficiency also suppressed anchorage-independent growth and formation of xenografts from ovarian cancer cell lines." (PMID 26716645, 2016). "CPT1A overexpression was associated with poor OS in patients with ovarian cancer." (PMID 34976793, 2021). "Overexpression of CPT1A is associated with poor prognosis of ovarian cancer patients." (PMID 26716645, 2016). "In our previous research, CPT1A had been identified to be differentially expressed with significance in paclitaxel-resistant ovarian cancer cell line A2780, and inhibition of CPT1A resulted in a prominent decrease of paclitaxel-resistant phenotype." (PMID 40709184, 2025). "In contrast, the deletion of NK2 homeobox 8 enhances FAO activity, significantly increasing the enrichment of H3K27 acetylation on the CPT1A promoter, leading to fatty acid metabolic reprogramming in epithelial ovarian cancer cells and platinum resistance." (PMID 41219902, 2025). "This is associated with an increase of fatty acid oxidation, which strongly depends on CPT1A, a transport protein which has been found overexpressed in ovarian cancer." (PMID 38491077, 2024). "The role of CPT1A in the amiodarone efficacy over epithelial ovarian cancer models was investigated." (PMID 38491077, 2024). "CPT1A upregulation in ovarian cancer promotes anoikis, and the inhibition of CPT1A leads to decreased cancer cell proliferation and migration." (PMID 38610991, 2024). "Increasing evidence suggests that FAO genes, represented by CPT1A, have become potential therapeutic targets in ovarian cancer, especially high-grade plasmacytoid ovarian cancer (HGSOC)." (PMID 39596847, 2024). "CPT1A is highly expressed in ovarian cancer and upregulated FAO mediated by CPT1A to promote ovarian cancer progression." (PMID 38783346, 2024). "Here, we find that CPT1A regulates mitochondrial dynamics and promotes mitochondrial fission in ovarian cancer cells." (PMID 37291333, 2023). "In order to understand the underlying mechanisms of CPT1A in drug-resistant ovarian cancer, a PPI network of CPT1A and 229 synergistic genes was constructed using the STRING database." (PMID 38003694, 2023). "It is also interesting why HSP27-knockdown ovarian cancer cells exhibit higher levels of CPT1A, the rate limiting enzyme of FAO, as well as higher lipid peroxidation upon cisplatin treatment." (PMID 37628819, 2023). "Previously, our study showed that carnitine palmitoyltransferase 1A (CPT1A) is highly expressed in ovarian cancer cells and promotes the development of ovarian cancer." (PMID 37291333, 2023). "We have shown that in response to cisplatin treatment, HSP27-knockdown ovarian cancer cells upregulate CPT1A, the rate-limiting enzyme of FAO." (PMID 37628819, 2023). "Overall, CPT1A regulates mitochondrial dynamics through MFF succinylation to promote the development of ovarian cancer." (PMID 37291333, 2023). "Since it is widely agreed that platinum resistance often correlates with paclitaxel resistance due to the cross-resistance effect, we aimed to explore the role of CPT1A in the occurrence of paclitaxel resistance in ovarian cancer." (PMID 38003694, 2023).